BRCA1 (BRCA1 DNA repair associated)
Diseases named in the same sentence as BRCA1 in open-access papers (continued):
Sharing a sentence is not in itself a finding about the gene and the disease.
breast cancer (continued). "The results of this prospective cohort study will provide valuable information regarding the risk reducing potential of modifiable risk factors for breast cancer in unaffected BRCA1 and BRCA2 gene carriers." (PMID 23517070, 2013). "Mutations of the breast and ovarian cancer susceptibility gene 1 (BRCA1) account for about 40–45% of hereditary breast cancer cases." (PMID 23802008, 2013). "Any advances in this topic would advance the current knowledge of BRCA1 associated breast cancer development." (PMID 23388117, 2013). "Several studies have shown a clear association between older age and development of ER+ breast cancers in BRCA1 mutation carriers." (PMID 23704984, 2013). "A proteomic study using mouse Brca1-deficient mammary tumours has recently reported TOP1 as up-regulated therefore strengthening our findings." (PMID 23805307, 2013). "BRIP1 (also known as BACH1 and FANCJ) is a DNA helicase that interacts directly with the breast cancer susceptibility protein BRCA1." (PMID 24040146, 2013). "The success of the PARP-1 inhibitor olaparib in BRCA1-deficient breast cancer and the early translational work in HNSCC underpin the importance of future targeted therapy in exploiting synthetic lethality in DNA repair." (PMID 24364026, 2013). "Both the immunohistochemical and molecular features observed in the ACC are typical of BRCA1-associated breast cancers and suggest an involvement of the patient’s germline mutation in the disease." (PMID 23374397, 2013). "In agreement with our findings, SNP rs13281615 was associated with increased risk of breast cancer among people at higher risk (who have positive family cancer history or BRCA1/BRCA2 mutation)." (PMID 24171766, 2013). "Pathogenic germline mutations in BRCA1 or BRCA2 are detected in less than one third of families with a strong history of breast cancer." (PMID 23704984, 2013). "As sporadic TNBC has clinical and molecular similarities to BRCA-1-associated breast cancers, there has been significant interest in using platinum compounds in TNBC." (PMID 23983689, 2013). "The identification of breast cancer susceptibility genes, particularly BRCA1 and BRCA2, has revolutionized the management of women with a family history of the disease." (PMID 23941127, 2013). "Since 2003, the BCCA has operated a high-risk screening clinic, offering annual breast cancer screening with MRI and mammography to confirmed BRCA1/2 mutation carriers." (PMID 23837641, 2013). "These included variants from three loci (19p13, 6q25.1, 12p11) previously associated with breast cancer risk for BRCA1 mutation carriers." (PMID 23544013, 2013). "The pronounced association between BRCA1/2 mutations and specific molecular subtypes strongly indicates that mutation carriers are, not only predisposed to develop breast cancer, but also to develop specific subtypes of breast cancer." (PMID 23704984, 2013). "Downstream inhibition of PI3K has also been shown to induce a BRCA1/2 deficiency in breast cancer cell lines." (PMID 24364026, 2013). "The purpose of this study was to calculate the cost-effectiveness of MRI screening for breast cancer in BRCA1/2 mutation carriers in a Canadian setting." (PMID 23837641, 2013). "The spectrum of BRCA1 gene mutations in breast cancer patients in various populations has been investigated." (PMID 23405268, 2013). "5%–10% of breast cancer cases are hereditary and are caused by pathogenic mutations in the considered reference BRCA1 and BRCA2 genes." (PMID 23586058, 2013). "Germline mutations in the BRCA1 gene confer an estimated lifetime risk of 60%–80% for breast cancer and 15%–60% for ovarian cancer." (PMID 24832651, 2013). "By comparing protein expression levels with RNA levels, a recent proteomic study using mouse Brca1-deficient mammary tumours clearly showed that RNA levels can be discordant with their protein expression." (PMID 23805307, 2013).
breast cancer (continued). "The landscape of genetic risk factors for breast cancer is known to be diverse, ranging from rare high-risk alleles, like BRCA1 and BRCA2, to common polymorphisms that only confer a minor breast cancer risk increase." (PMID 23383274, 2013). "Since the discovery of the breast cancer susceptibility genes BRCA1 and BRCA2 in 1994, a total of 18 breast cancer-associated susceptibility genes have been identified." (PMID 23318652, 2013). "Some of the key genetic mutations associated with breast cancer, such as BRCA1 and BRCA2 (human genes that belong to a class of genes known as tumor suppressors), have also been found in some individuals with prostate cancer." (PMID 24351742, 2013). "Germline mutations in the human breast cancer genes BRCA1 and BRCA2 account for a substantial proportion of familial, early-onset breast and ovarian cancers." (PMID 24137399, 2013). "- BRCA1 and BRCA2: The prototypic BRCA1 and BRCA2 mutations confer a very high life-time risk for breast cancer in the range of 55-85% for BRCA1 and 35-60% for BRCA2, compared with an about 10% population risk." (PMID 24025454, 2013). "Studies have found that BRCA1 mutations lead to a breast cancer risk of 40 to 87% and an ovarian cancer risk of about 16 to 68% by age 70, while BRCA2 mutations lead to a breast cancer risk of 40 to 84% and an ovarian cancer risk of 11 to 27% by that age." (PMID 23885284, 2013). "In 2011, AstraZeneca performed a proof of principal clinical trial on 54 subjects with BRCA1 or BRCA2 mutations with advanced breast cancer that were treated with PARP inhibitor olaparib." (PMID 23401782, 2013). "Somatic BRCA1 mutations are rare in sporadic breast cancer, but BRCA1 expression is downregulated in ∼30% of sporadic cases." (PMID 23863842, 2013). "BRCA1 was the first identified breast and ovarian cancer susceptibility gene responsible for approximately half of all inherited breast cancer cases." (PMID 23863842, 2013). "This phenotype is similar to 64–90% of human BRCA1-mutation breast cancers, so called ‘triple negative’ breast cancers." (PMID 24137399, 2013). "Further evaluation of 18 loci associated with breast cancer susceptibility in the general population found that only the TOX3, LSP1, 2q35 and RAD51L1 loci were significantly associated with breast cancer for BRCA1 carriers." (PMID 23544013, 2013). "The occurrence of rare histological types of breast cancers, including malignant phyllodes tumor, atypical medullary carcinoma and metaplastic carcinoma, in BRCA1 mutation carriers has been already reported." (PMID 23374397, 2013). "BRCA1 mutations confer upon women a breast cancer risk of about 60% and an ovarian cancer risk of about 40%; BRCA2 mutations confer a breast cancer risk of about 50% and an ovarian cancer risk of about 20%." (PMID 23638402, 2013). "The growth rates of breast cancer cells stably transfected with wt-BRCA1 and the mutated 3300delA were analyzed." (PMID 23393598, 2013). "Cao et al64 found that the frequency of disease-related germline mutations in PALB2 was 0.8% (3/360) in BRCA1/BRCA2-negative Chinese women with early-onset or familial breast cancer." (PMID 23318652, 2013). "Most of the tumors that develop in women with germline mutations in the BRCA1 breast cancer susceptibility gene are TNBC." (PMID 23825533, 2013). "Small subsets of the embryonic mammary epithelial signature were consistently activated in mouse Brca1-/- tumors and human basal-like breast cancers, which encoded predominantly transcriptional regulators, cell-cycle, and actin cytoskeleton components." (PMID 23506684, 2013). "Menopausal hormone therapy has been suggested to alter breast cancer risk in BRCA1 mutation carriers although the evidence is still limited." (PMID 23544014, 2013). "Carriers of BRCA1 or BRCA2 (BRCA1/2) mutations are at particularly high risk of breast cancer, with a 45-65% cumulative risk by age 70 years." (PMID 23837641, 2013).
breast cancer (continued). "Perhaps consistent with this is the observation that BRCA1-associated basal breast cancers better resemble aberrant luminal progenitor cells rather than the mesenchymal-like mammary stem cells." (PMID 23537295, 2013). "BRCA1/2 are high-penetrance breast cancer predisposition genes identified by genome-wide linkage analysis and positional cloning." (PMID 24205004, 2013). "As compared with BRCA2-associated breast cancer, BRCA1-associated breast cancer had a higher ER-negative rate and larger tumor diameter." (PMID 23318652, 2013). "Of course, some genes or even sets of genes are involved in multiple disease phenotypes; for example BRCA1 (Entrez GeneID: 672) is implicated in forms of both breast cancer and Fanconi Anemia." (PMID 23398688, 2013). "This study aimed to determine the prevalence of BRCA1 mutations in a Greek cohort of 106 familial ovarian cancer patients that had strong family history or metachronous breast cancer and 592 sporadic ovarian cancer cases." (PMID 23536787, 2013). "To illustrate, women with mutations in the BRCA1 or BRCA2 genes have a 50%–80% chance of developing breast cancer in their lifetimes." (PMID 25411643, 2013). "Women who carry a BRCA1 germ line mutation have a cumulative lifetime risk of 50–85% of developing breast cancer." (PMID 23863842, 2013). "A meta-analysis of 22 studies by Antoniou and colleagues found the cumulative risk of breast cancer by age 70 to be 65% in BRCA1 and 45% in BRCA2 mutation carriers." (PMID 23941127, 2013). "In contrast to data on BRCA1 mutation frequency in the female breast cancer population, these data in the general population are very limited." (PMID 24348557, 2013). "Studies in humans have shown that breast cancer with BRCA1 mutations and less commonly BRCA2 mutations display predominantly a triple negative immunophenotype with distinct basal-like subtype." (PMID 24004841, 2013). "The results of a European cohort study associates diagnostic radiation before the age of 30 with an increased risk of breast cancer among BRCA1/2 mutation carriers." (PMID 24094113, 2013). "For the two SNPs associated with breast cancer with P<10−5, neither rs619373, located in FGF13 (Xq26.3), nor rs184577, located in CYP1B1-AS1 (2p22-p21), was associated with breast cancer risk in the general population or among BRCA1 mutation carriers." (PMID 23544012, 2013). "The cost-effectiveness of using MRI and mammography in combination to screen for breast cancer in BRCA1/2 mutation carriers is finely balanced." (PMID 23837641, 2013). "The complete loss of PTEN is also a common event in breast cancers that are caused by breast cancer 1 (BRCA1) deficiency." (PMID 23514585, 2013). "Germline mutations in NBS1, RAD50, and MRE11 genes, although seen in low frequencies and can be population specific, can be qualified as novel candidates for breast cancer susceptibility in a subset of non-BRCA1 and BRCA/2 families." (PMID 23586058, 2013). "A separate locus at 10q23.5 provided strong evidence of association with breast cancer risk for BRCA1 carriers." (PMID 23544013, 2013). "The BRCA1 protein is inactivated in most familial cases with BRCA1 mutations and is under-expressed in about 30% of sporadic breast cancers, mainly in high grade tumours and in “basal-like” or “triple-negative” (ER-, PR-, HER2-) tumours." (PMID 23805307, 2013). "Several studies have reported that sporadic TNBC shares clinical and pathological features with hereditary BRCA1-related breast cancers, and, more recently, a case of a BRCA1 mutation carrier with an ACC of the breast was reported." (PMID 24191209, 2013). "Carriers of inherited mutations in the BRCA1 gene are prone to the development of breast cancer, mainly invasive ductal or medullary type carcinomas." (PMID 23374397, 2013). "For example, the breast cancer lifetime risks for the 5% of BRCA1 carriers at lowest risk are predicted to be 28–50% compared to 81–100% for the 5% at highest risk." (PMID 23544013, 2013).
breast cancer (continued). "In the mouse mammary tumor models, PARPi was more effective when P-gp knockout condition was added to BRCA-1 deficient cells." (PMID 23450678, 2013). "Consistent with this study, similarly lower BRCA1 mutation prevalence rates in black patients compared with white patients were reported in 2 other population-based series of patients with breast cancer." (PMID 24348557, 2013). "The current analyses suggest that 10 loci are now known to be associated with breast cancer risk for BRCA1 mutation carriers: 1q32, 10q25.3, 19p13, 6q25.1, 12p11, TOX3, 2q35, LSP1 and RAD51L1 all reported here and TERT." (PMID 23544013, 2013). "Recently, BRCA1 mutations have been shown to render breast cancer tumors sensitive to poly (ADP-ribose) polymerase (PARP) inhibition." (PMID 23855721, 2013). "Germ line mutations in BRCA1 confer increased susceptibility of developing breast cancer with high penetrance." (PMID 23388117, 2013). "So far, three truncating SLX4 mutations have been reported in 2,625 non-BRCA1/2 breast cancer patients in all published work, including this study." (PMID 23840564, 2013). "The identification of the two most prevalent susceptibility genes in breast cancer, BRCA1 and BRCA2, was the beginning of a sustained effort to uncover new genes explaining the missing heritability in this disease." (PMID 23409019, 2013). "Wang et al39 reported an 118A>T mutation in the 5′-untranslated region of the BRCA1 gene in sporadic breast cancers." (PMID 23318652, 2013). "BRCA1-associated breast cancers are associated with particular features such as early onset, poor histological differentiation, and hormone receptor negativity." (PMID 23405268, 2013). "KIT is co-expressed with EGFR and is associated with BRCA1-mutation carriers and in sporadic basal-like breast cancer." (PMID 23593654, 2013). "More specifically, a pancreatic ACC was reported in a BRCA1 male mutation carrier with a family history positive for early-onset breast cancers." (PMID 23374397, 2013). "According to percent of cells showing expression of studied genes, we have observed lower values in patients with breast cancer history in all types of BRCA1 mutations." (PMID 23553196, 2013). "Because women with a germline mutation in BRCA1 have such a drastically increased incidence in breast cancer risk, this mutation afforded the opportunity to examine how the DEABM would perform in reproducing cumulative risk of breast cancer over time." (PMID 23704974, 2013). "Individuals with HBOC syndrome have a 50% to 80% lifetime risk of developing breast cancer, suggesting the crucial role of loss-function of BRCA1 in the development of breast cancer." (PMID 23945289, 2013). "BRIP1 encodes a protein that was identified as a binding partner of BRCA1 and was investigated as a breast cancer predisposing gene." (PMID 23586058, 2013). "PGD is therefore addressed to carriers the mutation in the BRCA1 gene wanted to deprive their future children a substantial risk of breast cancer." (PMID 23941236, 2013). "Based on the joint distribution of the known BRCA1 breast cancer risk-modifying loci, we estimated that the breast cancer lifetime risks for the 5% of BRCA1 carriers at lowest risk are 28%–50% compared to 81%–100% for the 5% at highest risk." (PMID 23544013, 2013).
breast cancer (continued). "Studies have shown that breast cancers in women with germ-line BRCA1 mutations are more likely to be triple-negative and high-grade." (PMID 29147345, 2013). "Studies conducted in Taiwan had suggested that the mutation of BRCA1 contributes little to the occurrence of breast cancer." (PMID 23405268, 2013). "Items used in quality scoring for studies of the association between polymorphic repeat length in the AIB1 gene and breast cancer risk in BRCA1 and BRCA2 mutation carriers." (PMID 23483928, 2013). "Rao et al47 applied the BRCApro, Penn, and Myriad models to 212 Chinese familial breast cancer patients, among whom 33 had BRCA1 or BRCA2 mutations." (PMID 23318652, 2013). "In previous studies of unselected breast cancer cases only 3 to 10% of patients diagnosed at less than age 45 years were reported to carry a BRCA1/2 mutation." (PMID 23704984, 2013). "None of these studies considered PARP-1 activity together with BRCA1 functional status, except in the case of BRCA1-mutated cancers, which represent only around 5% of all breast cancers." (PMID 24191908, 2013). "Chan et al41 reported that in a Chinese population the BRCA1 promoter region polymorphism rs11655505 significantly reduces breast cancer risk in genotypes CT/TT (OR = 0.64, 95% CI = 0.47–0.88, P = 0.005) as compared with the CC genotype." (PMID 23318652, 2013). "Whole genome sequencing in breast cancer identified a characteristic distribution of single nucleotide mutations with an increased overall mutation burden in both BRCA1- and BRCA2-associated tumors." (PMID 24265793, 2013). "After replication testing of 89 SNPs showing the strongest association, with 5,986 BRCA1 mutation carriers, a locus on 19p13 was shown to be associated with breast cancer risk for BRCA1 mutation carriers." (PMID 23544013, 2013). "Although BRCA1 was associated with the genesis, progression, and prognosis of young breast cancer patients, they only accounted for about 5% of breast cancer occurrences." (PMID 23635316, 2013). "In this study, BRCA1 deficiency led to the loss of transcriptional repression of satellite DNA in mouse mammary tumors, human breast cancers, and cultured cells and to loss of ubiquitinated histone H2A within the satellite repeats." (PMID 23802008, 2013). "For example, variation in the genomic region surrounding HMMR/RHAMM, and the HMMR/RHAMM gene, modifies the risk to develop breast cancer in carriers of germline BRCA1 mutations." (PMID 23328114, 2013). "Patients with history of breast cancer have higher expression rate of BRCA1; however, regarding to mutation of this gene function its product is impaired." (PMID 23553196, 2013). "Women with mutations in BRCA1 or BRCA2 are at high risk of developing breast cancer and, in British Columbia, Canada, are offered screening with both magnetic resonance imaging (MRI) and mammography to facilitate early detection." (PMID 23837641, 2013). "Characteristics of observational studies of the relation between polymorphic repeat length in the AIB1 gene and breast cancer risk in BRCA1 and BRCA2 mutation carriers included in the meta-analysis." (PMID 23483928, 2013). "Approximately 7% of all breast cancers present a familial breast cancer history, and around 25% of these have germline mutations in BRCA1 and BRCA2 genes." (PMID 23326384, 2013). "In the Chinese population, as compared with sporadic breast cancer, BRCA1-associated breast cancer had a higher pathologic grade, and higher percentages of CerbB-2-negative and triple negative (ER/PR/CerbB-2-negative) tumors." (PMID 23318652, 2013).